TXNIP (thioredoxin interacting protein)
Diseases named in the same sentence as TXNIP in open-access papers (continued):
Sharing a sentence is not in itself a finding about the gene and the disease.
cancer (continued). "TXNIP also has the potential to act against immune cells in cancer by mediating the JAK-STAT, MAPK, and PI3K/Akt pathways." (PMID 36366411, 2022). "Some of the major signaling pathways critical to cancer progression/impediments have already been discussed in detail above, to demonstrate that TXNIP plays a significant role in cancer impediments." (PMID 36366411, 2022). "Our first pan-cancer study comprehensively revealed the carcinostatic role of TXNIP across different tumors." (PMID 35843949, 2022). "More recently, TXNIP has been shown to play a major role in cellular metabolism with implications on cancer through its inhibition of glycolysis and glucose uptake by downregulating the expression of GLUT1." (PMID 36077565, 2022). "Numerous preclinical studies have focused on upregulating TXNIP-driven molecules, which will soon lead to a much better way of treating various cancers." (PMID 36366411, 2022). "Under the hypoxia state, cancer cells accelerate the overexpression of GLUT1 through TXNIP inhibition as the cancer cell depends on glycolysis during the hypoxia condition." (PMID 36366411, 2022). "Bladder (n = 411), liver (n = 372) and lung (n = 566) cancer contribute to the top 3 tumors with the highest alteration frequencies of TXNIP, with an alteration frequency of 12.17%, 9.95%, and 9.89%, respectively." (PMID 35843949, 2022). "TXNIP is now known to mediate several inflammatory signaling pathways and to be downregulated as cancer progresses." (PMID 36366411, 2022). "Overall, these findings suggest that TXNIP has the potential to regulate STAT3 signaling in immune cells involved in cancer development." (PMID 36366411, 2022). "It has recently been reported that D-allose induces the expression of thioredoxin-interacting protein (TXNIP) in several types of cancer." (PMID 35743212, 2022). "Several studies have provided experimental evidence for the immune modulatory role of TXNIP in cancer impediments." (PMID 36366411, 2022). "This review highlights the role of TXNIP in preventing cancer, as well as recent reports describing its functions in various immune cells, signaling pathways, and promoting action against cancer." (PMID 36366411, 2022). "This phenomenon is particularly important in cancer cells, wherein TXNIP is often epigenetically silenced, thereby leading to a potentially amplified effect of both IGF1 and insulin on mitosis." (PMID 36291127, 2022). "And then, the survival status, genetic alteration as well as the immune infiltration of TXNIP in different cancers were identified." (PMID 35843949, 2022). "We then selected the specific cancers in which TXNIP was correlated with oncologic outcomes and infiltrating immune cells." (PMID 35843949, 2022). "We thus first explored the potential roles of TXNIP across thirty-three tumors mainly based on The Cancer Genome Atlas and Gene Expression Omnibus datasets." (PMID 35843949, 2022). "In this review, we discuss the implications of the immune modulatory function of TXNIP in various cancers and its role in mediating cellular damage in relation to the dependent cascade." (PMID 36366411, 2022). "The studies that have examined cancer obstructions at various signaling pathways to date have found limited evidence of TXNIP’s contribution." (PMID 36366411, 2022). "For cancers, as summarized previously, the concentration of TXNIP is low in cancers compared with normal cells, and downregulation of TXNIP indicates a poor prognosis." (PMID 35450411, 2022). "TXNIP also inhibits proliferation and migration in cancer cells, although TXNIP levels decrease, and function diminishes in various cancers." (PMID 35450411, 2022). "Multiple sources of evidence have demonstrated TXNIP’s irregular expression and prognostic role in many cancer types and provided an understanding of the various molecular processes involved in developing malignant phenotypes." (PMID 36366411, 2022).
cancer (continued). "Here, we first utilized data from the TCGA and Genotype-Tissue Expression (GTEx) data portals to investigate the expression profiles of TXNIP in various types of cancer and paired normal tissues." (PMID 35843949, 2022). "TXNIP has been predicted to control and introduce various immune cells and signaling pathways in cancer." (PMID 36366411, 2022). "OS analysis data showed a correlation between low TXNIP expression and poor prognosis for cancers of KIRC (P = 2.0e−04) within the TCGA project." (PMID 35843949, 2022). "TXNIP has attracted significant research interest owing to its involvement in glucose homeostasis, cancer, and neurodegenerative diseases." (PMID 36059548, 2022). "We applied multiple immune deconvolution approaches to obtain positive correlations between TXNIP expression and the immune infiltration levels of diverse TIICs in various types of cancers." (PMID 35843949, 2022). "In cancer cells, the glycolytic inhibitor 2-deoxyglucose (2DG) induced TXNIP transcription, and this process is partially due to the inhibition of OGA and an increase in the cellular O-GlcNAc modified proteins." (PMID 35887161, 2022). "In view of the complex biological functions of TXNIP, it is necessary to carry out a multi-dimensional pan-cancer expression analysis of TXNIP and further assess its potential molecular mechanisms." (PMID 35843949, 2022). "This evidence suggests that TXNIP plays an important role in cancer and is required for targeted therapy." (PMID 36366411, 2022). "TXNIP is known to play a crucial role in immune cells and immune responses during the progression of cancer." (PMID 36366411, 2022). "Recent studies showed that the exosomal miR-27a-3p produced by M2 macrophages enhanced the progression of HCC by downregulating TXNIP and stimulating the cancer stemness of HCC." (PMID 36366411, 2022). "Although the p-value was not less than 0.05, we found that MAFG with VDAC2 presented higher expression in paracancerous tissues than in cancer tissues, and TXNIP presented lower expression in paracancerous tissues than in cancer tissues." (PMID 34869576, 2021). "Our transcriptome data showing decreased expression of HSPA8 and increased expression of TXNIP upon treatment with synthetic rocaglates further support the previously suggested fundamental link between anabolic and catabolic processes in cancer cells." (PMID 34546000, 2021). "Thioredoxin-interacting protein (TXNIP) was first identified in cancer cells as a vitamin D3 target gene and later known as vitamin D3 upregulated protein 1 (VDUP1)." (PMID 33803178, 2021). "A parallel can be drawn from the medical studies, where it has been noted that D-allose has an effect on the proliferation of cancer cells by upregulating the expression of thioredoxin-interacting protein (TXNIP)." (PMID 33808719, 2021). "Researchers found that a low level of TXNIP expression in cancer results in high cancer cell growth." (PMID 33451071, 2021). "LoVo-R markedly downregulate TXNIP, an important redox regulator which is frequently reduced in cancer through epigenetic mechanisms." (PMID 34067290, 2021). "Earlier studies have identified D-allose to have significant antiproliferative properties in several types of cancer cells through the activation of the transcription factor MondoA:Mlx and the induction of TXNIP expression." (PMID 33302545, 2020). "This study also showed in a large series of human prostate benign hyperplasia and cancer samples that there was significantly less TXNIP expression in the cancer samples." (PMID 33302545, 2020). "As decreased levels of TXNIP correlate with the increased growth of different types of cancer cells, this issue needs to be considered." (PMID 33302545, 2020). "For example, it has been reported that TXNIP can increase cell apoptosis and inhibit proliferation, migration and invasion in cancer cells such as non-small cell lung cancer, liver cancer, pancreatic cancer and triple-negative breast cancer." (PMID 33233497, 2020).
cancer (continued). "TXNIP was suggested to act as a tumor suppressor protein and was found to be downregulated in several cancers." (PMID 33081035, 2020). "TXNIP is a multifunctional protein involved in a variety of cellular processes, including the regulation of differentiation, the cell cycle, cancer, cell aging, metabolism, inflammation, and immune cell regulation." (PMID 33327533, 2020). "TXNIP, one of the differentially expressed genes, is a well-established regulator of glucose metabolism and is regulated by c-Myc in some cancer cells." (PMID 33106166, 2020). "Our previous work demonstrated that a number of progrowth pathways inhibit MondoA transcriptional activity and TXNIP expression, suggesting a potential limitation of protein synthesis inhibitors as cancer therapeutics." (PMID 33292639, 2020). "In contrast to this, cancer cells are often highly glycolytic, and accordingly, frequently exhibit TXNIP downregulation." (PMID 32764426, 2020). "Previous studies have shown that TXNIP is a cancer suppressor gene in numerous solid tumors and hematological malignancies." (PMID 33106166, 2020). "In the total cohort, negative TXNIP expression was found in 73%, weak TXNIP expression was found in 14% of all cancers, moderate TXNIP expression was found in 8%, and strong TXNIP expression was found in 5% of all cancers." (PMID 33081035, 2020). "Accordingly, low TXNIP expression was found in 12.6% of all cancers, while high TXNIP expression was found in 87.4% of all cancers." (PMID 33081035, 2020). "We, therefore, detected TXNIP protein expression in human cancer cell lines and paired mouse xenograft tumors." (PMID 33081035, 2020). "When comparing adenocarcinomas with carcinomas derived from squamous cells, adenocarcinomas demonstrated higher numbers of TXNIP-positive tumors." (PMID 33081035, 2020). "Mutation in the chromosome region maintenance 1 (CRM1) binding domain of TXNIP suppresses HIF-1α nuclear export in cancer cells." (PMID 31615975, 2019). "Downregulation of TXNIP exacerbates cancer progression, and its expression is actually reduced in various human cancer cells." (PMID 31652503, 2019). "Collectively, our data suggest that the MondoA/TXNIP axis plays a critical role in how cancer cells sense and respond to dysregulated pH." (PMID 30717828, 2019). "Since inhibition of proliferation by Akt signaling induces “cancer dormancy” and protects cancer cells from ROS induced apoptosis, TXNIP likely plays a role in selection of resistant clones." (PMID 30627326, 2018). "Depleted or repressed TXNIP expression has been reported in breast cancer, non-small cell lung carcinoma, gastric cancer, and colon cancer, and other cancers." (PMID 29996811, 2018). "It has been reported that LAST2, DKK1 and TXNIP are targeted by miRNA‐372/373 in different cancer cells." (PMID 30171794, 2018). "Although TXNIP was originally identified in HL-60 cells as the VDUP1, reports on the ability of 1,25(OH)2D3 to induce its expression in cancer cells of diverse tissue origins are sparse, and have been largely limited to HL-60 cells." (PMID 29534438, 2018). "Although these observations raised the possibility of TXNIP as a target for cancer therapies, a clinical application focusing on this molecule has not been developed so far." (PMID 30410860, 2018). "TXNIP has been shown to be regulated through epigenetic modification during cancer development, such as DNA methylation and histone deacetylation." (PMID 28029659, 2017). "TXNIP has also been demonstrated to be the target of PRC2, and the PRC2 inhibitor, 3-Deazaneplanocin A (DZNep), can preferentially induce apoptosis in cancer cells through the induction of TXNIP." (PMID 28029659, 2017). "In contrast, in cancer cell models, up-regulation of TXNIP led cells to apoptosis and growth arrest." (PMID 28842639, 2017). "MiR-373 up-regulates and activates two important EMT inducers, HIF1α and TWIST, by directly inhibiting TXNIP to drive cancer cell EMT." (PMID 26196741, 2015).
cancer (continued). "In the cell, the endogenous inhibitor of Trx1 is the thioredoxin-interacting protein (TXNIP), which is dramatically downregulated in various human cancers." (PMID 26273424, 2015). "To determine the prognostic significance of TXNIP expression in human cancers, we performed survival analyses using TXNIP expression as the sole predictor of survival time." (PMID 20844768, 2010). "The role of TXNIP in cancer is complex and varies depending on the cancer type and stage." (PMID 41545347, 2026). "However, different studies have mitigated this initial assumption, suggesting that the role of TXNIP is complex in cancer." (PMID 40260243, 2025). "The results of our study suggest that the Trx system, which consists of TXN, TXNRD1, and TXNIP, may be useful for the early diagnosis and monitoring of cancer." (PMID 39744566, 2025). "Altogether, we identified TXNIP as an immunometabolic regulator of T cell activation, highlighting the complexity and great potential of immunometabolism for the development of future therapies against cancer." (PMID 40260243, 2025). "While the precise mechanisms behind its cancer cell-specific cytotoxicity are still under investigation, our findings suggest that TXNIP might inhibit cancer cell growth and survival by activating IL-24 signaling." (PMID 40175348, 2025). "Repression of TXNIP expression is a relevant step in cancer cell transformation." (PMID 39364720, 2025). "Third, although our findings indicate that TXNIP may suppress cancer cell growth through IL-24 signaling, the exact mechanisms remain unclear and require further investigation." (PMID 40175348, 2025). "Clarifying the functions of TXNIP may be crucial for elucidating the anti-cancer mechanisms of BET inhibitors." (PMID 41249136, 2025). "Exploring these interactions in patient samples could reveal valuable prognostic markers or therapeutic targets, enhancing our understanding of TXNIP and its targets in cancer pathogenesis and treatment response." (PMID 40175348, 2025). "In contrast, Elevated expression of TXNIP may also contribute to worse prognosis in some types of cancer." (PMID 40182050, 2025). "We additionally explored TXNIP expression in cancer patients." (PMID 40260243, 2025). "Additionally, TXNIP overexpression has been reported to suppress the proliferation of carcinoma cells by triggering apoptosis via activating the MAPK signaling pathway." (PMID 40558539, 2025). "Significantly down-regulated genes in cancer tissue, compared to normal tissue included PLA2G2A, MUC4, PCK1, TXNIP, and genes encoding the CCR7 ligands, CCL19 and CCL21, which are lymphoid chemokines involved in the chemotaxis of lymphoid cells such as leukocytes and dendritic cells." (PMID 38505585, 2024). "We therefore used siRNA-mediated TXNIP knockdown to assess whether the effects of Dpep on cancer cell survival are mediated by TXNIP." (PMID 38920655, 2024). "An improved understanding of the functions and mechanisms of TXNIP in cancers may enhance its suitability as a therapeutic target." (PMID 37794178, 2023). "Downregulation of TXNIP maintains the Trx/Trx reductase (Trx/TrxR) system in an active state, driving epithelial-mesenchymal transition and increasing the metastatic potential of cancer cells." (PMID 37794178, 2023). "This coordination of nutrient availability, i.e., low TXNIP levels and high glucose uptake, with nutrient use, i.e., Myc-driven synthesis of glucose-derived macromolecules, is likely important for supporting growth and proliferation of many cancer types." (PMID 36930677, 2023). "We also determined that differential regulation of TXNIP in normal and cancer cells may provide an opportunity for precision therapeutic targeting to improve efficacy and diminish potential toxicity." (PMID 36860653, 2023). "A pan-cancer study recently reported a correlation between TXNIP and infiltration of immune cells, supporting the idea that TXNIP may be an important player in determining the immunological makeup of the TME." (PMID 37794178, 2023).
cancer (continued). "Furthermore, TXNIP has been shown to play a role in the regulation of cell proliferation and apoptosis in cancer cells." (PMID 37240157, 2023). "The negative association of c-Myc with TXNIP in Pan-Cancer in TCGA dataset indicates that c-Myc generally suppresses TXNIP expression in different types of cancers." (PMID 37095099, 2023). "In the context of cancer treatment, TXNIP agonists hold great potential as antitumor agents." (PMID 37794178, 2023). "This analysis revealed that in addition to enhanced mitochondrial iron and ROS levels, the suppression of NAF-1 function in cancer cells resulted in the enhanced expression of thioredoxin interacting protein (TXNIP), which binds thioredoxin (TRX) and induces oxidative stress." (PMID 36009251, 2022). "In cancer, preclinical studies are conducted on many approaches targeting TXNIP regulation." (PMID 36366411, 2022). "In recent years, it has been found that TXNIP is abnormally expressed in various malignant tumors." (PMID 35414060, 2022). "TXNIP reduces cancer cell viability by arresting the cell cycle." (PMID 35743212, 2022). "However, a mechanistic approach is required to understand the therapeutic targets for TXNIP signaling in cancers that use other pathways." (PMID 36366411, 2022). "As a result, a moderator specifically targeting TXNIP is being developed for cancer treatment." (PMID 36366411, 2022). "On the other hand, it has been demonstrated mechanistically that when mTOR levels rise in cancer cells, it binds to MondoA directly in the cytoplasm and prevents the formation of the MondoA/Mlx complex which limits MondoA nuclear entry and TXNIP transcription and expression." (PMID 36366411, 2022). "TXNIP also has the capability of being a biomarker to predict prognosis in various cancers." (PMID 35450411, 2022). "Next, we analyzed the prognostic value of TXNIP expression across cancers in GEPIA2." (PMID 35843949, 2022). "Notably, decreased expression of TXNIP indicated poorer survival prognosis in seven out of eight cancers, including breast, bladder, skin, lung, brain, eye and soft tissue cancers (all P < 0.05)." (PMID 35843949, 2022). "To date, therapies targeting TXNIP in cancer are still under investigation." (PMID 36366411, 2022). "To figure out whether TXNIP expression correlates with cancer, we firstly evaluated TXNIP expression in different tumors and adjacent normal tissues using the online Oncomine database." (PMID 35843949, 2022). "TXNIP levels within cancer cells can be regulated by many factors." (PMID 35450411, 2022). "Therefore, TXNIP exhibits pro-oxidative stress, proinflammatory, and pro-apoptotic properties and thus has a huge role in cancer treatment." (PMID 36366411, 2022). "In the present in vitro study, Western blotting analysis indicated that D-allose stimulated TXNIP expression, consistent with previous studies on other cancer types, and the FACS analysis revealed the up-regulation of intracellular ROS levels after treatment with D-allose." (PMID 35743212, 2022). "In agreement with this notion, elevated TXNIP levels in LS may account for cancer protection in this pathology." (PMID 36291127, 2022). "Therefore, it is likely to be crucial for tumorigenesis when TXNIP expression is downregulated in cancers with constitutive PI3K/Akt/mTOR pathway activation." (PMID 36366411, 2022). "When TXNIP is overexpressed, it prevents the growth of cancer cells." (PMID 36366411, 2022). "The fact that ras and myc inhibit TXNIP expression while rapamycin upregulates it led us to hypothesize that TXNIP might play an important role during the initiation of cancer or induction of senescence by metabolic reprogramming." (PMID 36291127, 2022). "In addition, several consecutive studies have shown that cancer patients with elevated TXNIP expression have a better prognosis than those with reduced TXNIP expression, making TXNIP a potential therapeutic target for cancer treatment." (PMID 36366411, 2022).